TNF (tumor necrosis factor)
Diseases named in the same sentence as TNF in open-access papers (continued):
Sharing a sentence is not in itself a finding about the gene and the disease.
synovitis (140 papers, 2005 to 2025). Inflammation of a synovial membrane. "The OA-specific markers identified were mainly cartilage- (CTX-II, C2C) and synovitis-driven (TNF-α, IL-1), linked with cartilage degradation and high levels of systemic inflammation." (PMID 39497175, 2024). "Recent integrative histopathological and clinical observations support the notion that rheumatoid synovitis has different patterns and that TNF-α and IL-6 are the primary causes of the two most common types of synovitis in RA, myeloid and lymphoid synovitis." (PMID 38715981, 2024). "Overall, we demonstrated that p21-deficient CAIA mice were susceptible to joint cartilage destruction and severe synovitis via IL-1β- and TNF-α-induced inflammation in vivo." (PMID 34131243, 2021). "Inflammatory cytokines (e.g. TNF-α, IL-17, IL-1β and IL-6) are known to be pathogenic factors triggering joint diseases and established synovitis." (PMID 34950033, 2021). "Synovitis-induced pathological alteration causes the release of proinflammatory cytokines such as IL-1β and TNF-α." (PMID 34681754, 2021). "In synovitis lesions, lymphocytes and synoviocytes produce large amounts of inflammatory cytokines, such as TNF, interleukin (IL)-1, and IL-6, which cause synovitis." (PMID 32944095, 2020). "In other words, cartilage damage is dependent on TNF and IL-1 in the joints, causing synovitis, whereas the development of erosions is dependent on the formation of osteoclasts, which requires more TNF than does synovitis." (PMID 25994819, 2015). "Our results provide evidence of LLLT-dependent reduction of IL-1β, IL-6 and TNFα, and the therapy's ability to inhibit proliferation of inflammatory cells makes it a suitable treatment for synovitis associated with the early stages of OA." (PMID 24028507, 2013). "Diffuse or myeloid synovitis affects 50–70% of patients, is associated with good responses to anti-TNF drugs, and has one of the most benign clinical phenotypes, where rheumatoid factors tend to be absent, CD68+ cells predominate, and there are few lymphocytes and no ectopic lymphoid structures." (PMID 33968950, 2021). "Synovitis-associated pathological alteration of the joints causes the release of proinflammatory cytokine mediators, such as interleukin 1β (IL-1β) and tumor necrosis factor-α (TNF-α)." (PMID 34681754, 2021). "As TNFα drives inflammation in a number of inflammatory diseases, and OA is often associated with synovitis, these results corroborate the idea that NDMVs could have anti-inflammatory activity under these conditions." (PMID 34299030, 2021). "Furthermore, we found that anti-TNFα, when initiated prior to the development of longstanding synovitis, can prevent hemophilic arthropathy caused by repeated intra-articular hemorrhage in hemophilia B mouse model." (PMID 31892201, 2019). "Synovitis in RA develops as a result of infiltration of innate and adaptive immune cells causing a significant inflammatory response and cytokine release, including, but not limited to tumor necrosis factor alpha (TNF-α)." (PMID 25359150, 2014). "Synovitis and erosivity were lower in TNF-α/LT-α-deficient mice compared with wild-type controls." (PMID 17129374, 2006). "Given that transcriptional and translational overexpressions of IL-34 have been delineated in knee OA FLS treated with TNF-α and the inflamed synovium, whether its levels in the synovial fluid and circulation are associated with the severity of knee OA synovitis was determined in the current study." (PMID 32409720, 2020). "High-grade synovitis was characterized by lining hyperplasia, immune infiltration, enhanced NF-κB activity, and elevated TNF-α expression." (PMID 41301825, 2025). "During the clinical phase, TNF-α, IL-6, and IL-1β drive synovitis by activating macrophages and fibroblast-like synoviocytes, while also promoting RANKL (Receptor Activator of Nuclear factor κB Ligand) expression and osteoclast differentiation." (PMID 41010616, 2025).
synovitis (continued). "Histological analysis using hematoxylin and eosin (HE) and TRAP staining of the ankle joints illustrated more pronounced synovitis and an increased number of osteoclasts in Irg1−/−/TNF-Tg mice compared to Irg1+/+/TNF-Tg controls." (PMID 40500265, 2025). "Synovitis in RA is characterized by the continuous influx of immune cells and the production of various pro-inflammatory cytokines such as TNF, IL-1, IL-17, and IL-22, which stimulate bone and cartilage inflammation and damage." (PMID 39104791, 2024). "MMP13, which is upregulated in the joint by IL-1 and TNF, leading to articular cartilage destruction and synovitis, is widely studied as a promising target for several DMOAD candidates due to its OA-specific properties." (PMID 39408977, 2024). "Chronic synovitis leads to the release of cytokines, such as tumor necrosis factor (TNF) and interleukins (IL), along with other inflammatory mediators." (PMID 38856919, 2024). "Proinflammatory cytokines, such as IL-6, IL-1β, and TNF-α, contribute to the destruction of cartilage and synovitis." (PMID 38913985, 2024). "Previous works of literature reported that TNF-α and IL-1β are closely related to cartilage destruction and the occurrence of synovitis." (PMID 37187885, 2023). "In synovitis, the cytokines produced by synovial cells contain interleukin 1 (IL-1), IL-6, interleukin 17 (IL-17), and tumor necrosis factor-α (TNF-α), which increase detrimental mediators and aggravate synovial inflammation and cartilage deterioration." (PMID 37013568, 2023). "Synovitis is responsible for the production of proinflammatory cytokines such as interleukin-6 (IL-6), tumor necrosis factor-α (TNF-α), and interleukin-1β (IL-1β)." (PMID 37021049, 2023). "TP-VP NPs effectively down-regulated IL-1β, IL-6 and TNF-α levels to inhibit the erosion of synovitis and bone tissue, and alleviate the swelling and deformation of CIA mice’s feet." (PMID 35999774, 2022). "Once OA synovitis starts, IL-1, TNF-α and IL-6 are over-produced and secreted to synovial fluid through activation of TLR4 by synovial cells." (PMID 36241903, 2022). "Synovitis plays a vital role in the onset of OA through the production of HA and pro-inflammatory cytokines including tumor necrosis factor-α and interleukin 1β." (PMID 35236298, 2022). "TNF, derived from macrophages and chondrocytes, serves as an indispensable mediator in the degradation of the cartilage matrix and is closely related to synovitis, and it has been widely reported that many drugs interact with TNF to make an effect on OA." (PMID 34868222, 2021). "Since TNF-α is strongly associated with cartilage loss in OA and was poorly controlled with COX and sEH inhibition in our synovitis model, we tested the effects of COX and sEH inhibition on TNF-α-induced apoptosis of primary equine articular chondrocytes." (PMID 34422942, 2021). "An equine model of amphotericin B-induced synovitis showed a delayed but sustained elevation of IL-1β and TNF-α over the 9-week study period." (PMID 33980227, 2021). "Synovitis, involving the infiltration of mononuclear cells into the synovial membrane and the production of proinflammatory mediators, including IL-1β, TNF-α and chemokines, is common in early stage and late stage disease." (PMID 33669093, 2021). "PGE2, IL-10, and TNF-α concentrations increased after one hour of LPS-induced synovitis in the present study, however, PGE2 had a higher peak concentration after 8 h." (PMID 32365982, 2020). "The synovitis scores as well as the levels of IL-1β and TNF-α suggested that PEMF reduced the severity of synovitis in vivo." (PMID 32596310, 2020). "Synovitis generates inflammatory mediators (TNF-α and IL-1β) that are released into the synovial cavity." (PMID 32566090, 2020). "Synovitis can be sustained by cytokines such as IL-1β and TNF-α, which can further promote the production of MMPs and other proteinases." (PMID 33053109, 2020).
synovitis (continued). "Pro-inflammatory cytokines, such as interleukin 1β (IL-1β) and tumor necrosis factor α (TNF-α), play a crucial role in the development of synovitis and progressive joint destruction." (PMID 33117381, 2020). "As observed in this study, after one hour of synovitis induction, all groups showed a significant increase in TNF-α concentration." (PMID 32365982, 2020). "On the other hand, macrophages stimulated with cartilage fragments upregulated number of genes that are predominantly expressed in synovitis of OA patients such as TNF, CCL9, CXCL16, and PTGES15,16,21,26–29." (PMID 32371954, 2020). "We further confirmed TNF-alpha expression in the synovial tissue derived from another patient with synovitis by immunohistochemistry and showed TNF-alpha expressed within the inflamed synovial tissue." (PMID 31603905, 2019). "Hemophilic arthropathy (HA) typically begins with proliferative synovitis that shares some similarities with inflammatory arthritides, in which the proinflammatory cytokine tumor necrosis factor (TNF)-α has a crucial pathogenetic role." (PMID 31261789, 2019). "Early reports of TNF-alpha inhibitor use to control AF lesions involved patients with SAPHO syndrome (Synovitis, Acne, Pustulosis, Hyperostosis, and Osteitis) who had failed conventional treatments." (PMID 33655144, 2018). "Although this paper has not been focused on the biological mechanisms, which promote the decrease of TNF-α in the synovitis model, the bibliography has several references that support the association between exo-MSCs and TNF-α." (PMID 28377922, 2017). "We are interested in investigating the difference between primary human synovial fibroblast (hSF) cells and SW982 as synovitis models induced by TNF-α and in monitoring their responses to sesamin as an anti-inflammatory phytochemical." (PMID 29237438, 2017). "In patients with grade 3 cases of synovitis, the levels of TNFα, IL1β, IL6, and MMP1 were significantly increased compared with those in cases of grade 2 synovitis (p < 0.05)." (PMID 28425031, 2017). "This is the first study to link increases in circulating Th17 cell numbers and IL17 production with resolution of ultrasonographic features of synovitis during anti-TNF treatment." (PMID 28010726, 2016). "Previously we reported that TNF-Tg mice develop ankle synovitis and significantly increased numbers of LYVE-1+ lymphatic vessels." (PMID 27239212, 2016). "It has been reported that the hip labrum and synovium of the hip joint of ONFH patients exhibited less synovitis, less TNF expression than that of OA." (PMID 25653475, 2015). "L. casei consumption prevented Salmonella-induced synovitis, the increment of TNF-α in knees and the increase of IL-17 expression in popliteal and inguinal lymph nodes." (PMID 24340048, 2013). "It has been shown that TNF-α production and synovitis are related to the expression of IL-17 in joint draining lymph nodes." (PMID 24340048, 2013). "Results of work in animals have suggested a central role of TNF-α and IL-1 in the process of synovitis and joint destruction." (PMID 22085488, 2011). "MRI synovitis has been shown to reduce significantly following anti-TNF therapy in PsA, and we found this to be the case in our combined group of clinical knee responders." (PMID 21272347, 2011). "The results suggest that these cytokines play a role in the pathogenesis of synovitis in osteoarthritic knees in different ways: TNFα is correlated with pain, whereas IL-6 is correlated with joint function." (PMID 21714933, 2011). "The results of the present study are comparable with those of previous studies, which using a zymosan-induced mouse OA model, reported that TNFα is related to synovitis and that IL-6 has a role in reducing cartilage destruction." (PMID 21714933, 2011). "A distinct TNF expression was observed in the lining layer as well as in sublining areas in synovitis, whereas HMGB1 and IL-1β expressions were most often restricted to the sublining areas." (PMID 17397533, 2007).
synovitis (continued). "Immunohistochemical studies have found that, particularly in early OA, this synovitis has a mononuclear cell infiltrate, with considerable production of proinflammatory cytokines like TNF-α and IL-1β and destructive enzymes like MMP-1 and MMP-3." (PMID 17177994, 2006). "Our synovial findings align more closely with Görtz’s TNF-driven synovitis model, suggesting that JNK activation in hip OA synovium may require specific inflammatory triggers beyond the basal TNF-α/IL-1β milieu." (PMID 41463004, 2025). "Additionally, several cytokines such as IL-6 and TNF-alpha cytokines have the potential promote synovitis, resulting in further joint inflammation and cartilage degradation." (PMID 39274226, 2024). "The rationale for using anakinra was to address the uncertainty between infectious and post-infectious synovitis, opting for a short-acting targeted treatment before committing to long-term therapy with conventional DMARDs, such as methotrexate or anti-TNF biological response modifiers." (PMID 39334678, 2024). "Synovitis, trauma or injury can lead to activation of the mechanoreceptors, which in turn can stimulate an inflammatory response with the release of pro-inflammatory cytokines and degradative enzymes (IL-1B and TNF-alpha and MMPs)." (PMID 39765549, 2024). "Current evidence suggests that MTX, TNF-α inhibitors and prednisolone may have a better efficacy on pain relief in patients with hand OA and synovitis." (PMID 38961031, 2024). "Synovitis has been related to the production of TNF-α, IL-17, IL-6, and IL-1." (PMID 37446881, 2023). "We explored whether TNF inhibition had any beneficial effects in the model of purified Lpp-induced synovitis by treating the mice with anti-TNF treatment (etanercept)." (PMID 36262324, 2022). "Furthermore, it has been observed that anti-TNF treatment changed the expression of glycosyltransferases in bovine synovitis." (PMID 35955616, 2022). "Collectively, these results suggests that Macrophages are an important biomarker and be a potential therapeutic target in OA synovitis, in which TNF signaling pathways may play a critical role in the pathogenesis of OA." (PMID 36685529, 2022). "Animal studies have assessed several treatments for synovitis that are designed to interfere with specific biological molecules, such as anti-tumor necrosis factor agents, anti-nerve growth factor antibodies, and antiproteases (anti-matrix metalloproteinases and anti-ADMATS)." (PMID 36443725, 2022). "The danger signals released by innate immune cells activate Th1 and Th17 lymphocytes leading to inflammation, synovitis, enthesitis and altered bone homeostasis; cytokines, such TNF-α, IL-17, IL-23, IL-1, and interferon-γ participate in these immunological mechanisms." (PMID 34200121, 2021). "Persistent synovitis is one of the characteristics of RA, which is mainly caused by the continuous migration of immune cells into the joints and the continuous production of various proinflammatory cytokines, of which chemokines, TNF-α, and IL-1β play a crucial role in synovitis." (PMID 34691317, 2021). "In RA, TNF-α and IL-6 are the two well-known cytokines triggering synovitis and bone erosions." (PMID 33343563, 2020). "Polyarticular PsA patients in remission had lower levels of local (US synovitis) and systemic inflammation than RA patients in remission, even though a significantly higher percentage of PsA patients were on tapered doses of anti-TNF, mainly in monotherapy." (PMID 33195301, 2020). "Senescence of cultured SF is accelerated upon exposure to TNFα or oxidative stress and may contribute to the pathogenesis of synovitis by increasing the production of pro-inflammatory mediators." (PMID 31708994, 2019). "In an animal model of synovitis, one group demonstrated a decrease in synovial lymphocytes together with downregulation of TNF-α transcripts in MSC-EV-treated joints, which may represent a promising therapeutic option for the treatment of synovitis." (PMID 30923617, 2019).
synovitis (continued). "Researchers in two large clinical studies reported a lack of association of radiographic outcome and synovitis in anti–tumour necrosis factor α (anti-TNF-α)–treated cohorts." (PMID 24886513, 2014). "Mild synovitis develops early in OA progression, where synovial immune cells produce inflammatory mediators such as interleukin-1β (IL-1β), tumor necrosis factor-alpha (TNF-α), and activated metalloproteinases (MMPs), further accelerating cartilage degradation." (PMID 40761349, 2025). "Synovitis, characterized by inflammation in the synovial tissue, plays a crucial role in perpetuating the disease by triggering a cascade of catabolic and proinflammatory mediators, including cytokines, such as interleukin (IL)-1 beta, tumor necrosis factor-alpha, and IL-13." (PMID 38711706, 2024). "The decrease of synovial lymphocytes, the downregulation of TNF-α transcripts, as well as the trend to improve the impulse in exosome-treated joints, point out that exosomes may represent a promising therapeutic option for the treatment of synovitis." (PMID 28377922, 2017). "To assess the functional significance of this increased lymphangiogenesis, we used a new in vivo MRI technology that we have developed to see whether the draining popliteal lymph nodes from the knee and ankle joints of TNF-Tg mice with synovitis are increased versus WT littermates." (PMID 17997858, 2007). "Inflammatory markers such as IL‐1β, IL‐6, TNF‐α and MMP1 increased with synovitis or severe chondral damage." (PMID 40989937, 2025). "TNF and IL-6 inhibitors, such as infliximab and tocilizumab, suppress VEGF production and are positively correlated with reductions in synovitis severity, as assessed by ultrasound." (PMID 41010616, 2025). "Urinary TNF-α and TGF-β1 levels positively correlated with body mass index and pain and synovitis score and immune cell infiltration, respectively." (PMID 39595987, 2024). "TNFα also up-regulates the levels of MMPs and PGE2 via fibroblasts and macrophages, leading to synovitis, bone resorption, and cartilage erosion." (PMID 37765197, 2023). "Expression levels of IL1B, IL6, CXCL8, TNF, PTGS2, and PTGER4 showed significant positive correlation with synovitis score." (PMID 33507995, 2021). "Expression levels of IL1B, IL6, CXCL8, TNF, PTGS2, and PTGER4 showed significant positive correlations with synovitis score." (PMID 33507995, 2021). "With regard to comparison of the low-grade and high-grade groups with different grades of synovitis, expression levels of IL1B, CXCL8, TNF, and PTGS2 were significantly higher in the high-grade group than in the low-grade group." (PMID 33507995, 2021). "A previous report has indicated that FA had the ability to decrease the levels of hydrogen peroxide-induced IL-1β, TNF-α, MMP-1, and MMP-13, thereby reducing bone destruction, synovitis, and the erosion of cartilage in antigen-induced arthritis." (PMID 24883069, 2014). "In contrast to TNF-α-driven models that predominantly exhibit inflammatory arthritis with synovial hyperplasia and cartilage erosion but minimal osteoproliferation, the CAIA paradigm uniquely manifests concurrent synovitis and intra-articular ossification." (PMID 40822862, 2025). "Our study demonstrates a positive correlation between BMI and urinary TNF-α, but not with the synovitis score or immune cell infiltration." (PMID 39595987, 2024). "Regarding cytokine production in normal synovium, although very small amounts of pro-inflammatory cytokines, such as interleukin-1β (IL1β), interleukin 6 (IL-6), and tumor necrosis factor-alpha (TNF) are generated, levels are much lower than those present in any type of synovitis." (PMID 33968950, 2021). "In the present study, the level of MMP1 was significantly higher in the synovial membrane of patients with diffuse synovitis, than in those with focal synovitis, suggesting that severe synovitis can progress to catabolic chondral degeneration via MMP1, which is mediated by TNFα and IL1β." (PMID 28425031, 2017).